CYP21A1P (cytochrome P450 family 21 subfamily A member 1, pseudogene)
Synonyms: P450c21A; formerly CYP21P; CYP21A
Gene: Transcribed unprocessed pseudogene on chromosome 6 (32,005,689 to 32,008,399, forward strand). Ensembl gene ENSG00000204338.
Diseases named in the same sentence as CYP21A1P in open-access papers:
CYP21A1P is named in the same sentence as 6 diseases in open-access papers, as found by Europe PMC text mining. Sharing a sentence is not in itself a finding about the gene and the disease. The quoted sentences say what the papers report.
congenital adrenal hyperplasia (8 papers, 2009 to 2025). Congenital adrenal hyperplasia (CAH) is an inherited endocrine disorder caused by a steroidogenic enzyme deficiency that is characterized by adrenal insufficiency and variable degrees of hyper or hypo androgyny manifestations, depending of the type and the severity of the disease. "We then apply PB-Motif to 26 clinical samples, characterizing CYP21A2 and its pseudogene CYP21A1P as part of a diagnostic assay for congenital adrenal hyperplasia." (PMID 34394200, 2021). "For example, in Taiwan’s newborn screening program, funded by the National Health Insurance, the pathogenic gene for congenital adrenal hyperplasia (CYP21A2) has a pseudogene, CYP21A1P, which increases the risk of diagnostic error." (PMID 41329681, 2025). "The non-allelic gene conversion in the background of the concerted evolution of CYP21 paralogues is well studied in humans, because congenital adrenal hyperplasia (CAH), a frequent Mendelian disorder mostly caused by gene conversion from CYP21A1P to CYP21A2, is a focus of human geneticists." (PMID 24312389, 2013). "The single laboratory method validations of duplex qPCR assays with hydrolysis probes on CYP21A1P and CYP21A2 genes, residing a CNV (RCCX CNV) and related to congenital adrenal hyperplasia, were performed using 46 human genomic DNA samples." (PMID 36454796, 2022).
21-hydroxylase deficiency (5 papers, 2010 to 2025). "Among them, the IVS2-13A/C>G mutation, originating from the CYP21A1P pseudogene, is the most common allele responsible for the SW form of 21-hydroxylase deficiency." (PMID 40724898, 2025). "CYP21A1P/A2 chimeric genes can be correlated with SW or SV forms of 21-hydroxylase deficiency depending on the mutations they carry." (PMID 20587039, 2010). "This study demonstrated high allelic variability for 30-kb deletion in patients with 21-hydroxylase deficiency indicating that a founder effect might be improbable for most monomodular alleles carrying CYP21A1P/A2 chimeric genes in Brazil." (PMID 20587039, 2010). "The genetic similarity and proximity between pseudogene CYP21A1P and functional gene CYP21A2 facilitate various cross-overs accounting for over 90% of all documented mutations linked to 21-hydroxylase deficiency." (PMID 38791102, 2024). "The complex genetic structure of the RCCX CNV complicates further the genetic diagnosis of 21-hydroxylase deficiency, in particular when a haplotypic structure with the segment harboring two CYP21A2 gene copies and one CYP21A1P pseudogene copy is involved." (PMID 37324257, 2023).
autoimmune disease (1 paper, 2024). A disorder resulting from loss of function or tissue destruction of an organ or multiple organs, arising from humoral or cellular immune responses of the individual to their own tissue constituents. "The CYP21A1P gene has been associated with all five autoimmune diseases with evidence from multiple tissues." (PMID 39590325, 2024). "In our results, we also find a variety of pseudogenes (HLA-DRB6, CYP21A1P, PSORS1C3) that have a significant effect on the risk of autoimmune diseases." (PMID 39590325, 2024).
CYP21A1P also shares sentences with these, for which no sentence is quoted: Ehlers-Danlos syndrome (1 paper); Gaucher disease (1); sarcopenia (1).